ITIH3 (inter-alpha-trypsin inhibitor heavy chain 3)
Description:
May act as a carrier of hyaluronan in serum or as a binding protein between hyaluronan and other matrix protein, including those on cell surfaces in tissues to regulate the localization, synthesis and degradation of hyaluronan which are essential to cells undergoing biological processes.
Synonyms: ITI-HC3; SHAP; H3P
Tractability: Antibody: its Gene Ontology location is reachable by antibodies, with high confidence; UniProt places it where antibodies can reach, with medium confidence; UniProt predicts a signal peptide or a membrane-spanning region. PROTAC: its protein half-life has been measured.
Gene: Protein-coding gene on chromosome 3 (52,794,450 to 52,809,881, forward strand). Ensembl gene ENSG00000162267.
Subcellular location: Secreted
Pathways (Reactome):
Hemostasis: Platelet degranulation
Gene Ontology:
Molecular function: protein binding; endopeptidase inhibitor activity; serine-type endopeptidase inhibitor activity
Biological process: hyaluronan metabolic process
Cellular component: extracellular exosome; extracellular region; platelet dense granule lumen
Genetic constraint (gnomAD): Loss-of-function variants: 79 observed, 93.11 expected, observed/expected ratio (o/e) 0.85, 90% interval 0.71 to 1.02. The upper end of that interval is the gene's LOEUF score, 1.02, which puts it in group 4 of 6, group 1 being the genes least tolerant of losing a copy. Missense variants: 1,043 observed, 1,138.4 expected, observed/expected ratio (o/e) 0.92, 90% interval 0.87 to 0.96. Synonymous variants: 416 observed, 446.01 expected, observed/expected ratio (o/e) 0.93, 90% interval 0.86 to 1.01.
Homologues: Orthologues: chimpanzee ITIH3 (99% identical), macaque ITIH3 (97% identical), dog ITIH3 (89% identical), pig ITIH3 (86% identical), mouse Itih3 (85% identical), rabbit ITIH3 (84% identical), guinea pig ITIH3 (84% identical), rat Itih3 (83% identical), zebrafish itih3a.1 (49% identical), zebrafish itih3a.2 (48% identical), tropical clawed frog itih3 (43% identical). Paralogues in human: ITIH1 (55% identical), ITIH4 (42% identical), ITIH2 (40% identical), ITIH5 (33% identical), ITIH6 (33% identical), VWA3B (19% identical), PARP4 (19% identical), VWA5A (15% identical), VWA3A (15% identical), VWA5B1 (15% identical), VWA5B2 (13% identical).
Diseases named in the same sentence as ITIH3 in open-access papers:
ITIH3 is named in the same sentence as 78 diseases in open-access papers, as found by Europe PMC text mining. Sharing a sentence is not in itself a finding about the gene and the disease. The quoted sentences say what the papers report.
schizophrenia (15 papers, 2013 to 2024). A major psychotic disorder characterized by abnormalities in the perception or expression of reality. "Genome-wide association studies have also identified ITIH3 loci in a broad depression phenotype, emphasizing its role in the genetic correlation of depression traits and even schizophrenia." (PMID 38637810, 2024). "Polymorphisms in ITIH3 has been implicated in several diseases, including schizophrenia and major depressive disorder." (PMID 39221148, 2024). "Polymorphisms of ITIH3 have been associated with an increased risk for schizophrenia and major depressive disorder." (PMID 38375199, 2024). "We previously showed that a missense variant (rs3617) in the coding region of IHTI3 conferred schizophrenia risk by altering the protein abundance and function of ITIH3." (PMID 34978167, 2022). "Clozapine targeting ITIH3 and OXT is a second-generation antipsychotic medication classified as atypical, which is utilized in the management of treatment-resistant schizophrenia and to reduce the risk of suicide in individuals with schizophrenia." (PMID 39221148, 2024). "Based on this, three-step SMR and colocalization analyses identified ITIH3 and CCS as being related to the risk of developing depression, while CTSS and DNPH1 are related to the onset of schizophrenia." (PMID 38637810, 2024). "One example is the inter-alpha-trypsin inhibitor heavy chain gene family (ITIH1, ITIH3, ITIH4), which has been associated with major psychiatric disorders including MDD, bipolar disorder and schizophrenia." (PMID 30626913, 2020). "Our study revealed the complex genetic mechanisms of the ITIH3 locus in schizophrenia." (PMID 34978167, 2022). "Another OA risk gene ITIH3 (POA = 2.59 × 10–7, PMD = 5.27 × 10–6) interacts with antipsychotics clozapine and has been linked to depression, schizophrenia, and ASD, among other disorders." (PMID 34603368, 2021). "Through coloc analysis, ITIH3 was conclusively associated with the onset of depression, CCS exhibited associations with depression at both the gene and protein levels, and CTSS and DNPH1 were implicated in the onset of schizophrenia at both the gene and protein levels." (PMID 38637810, 2024). "Of interest, the ITIH3 region (3p21.1), ANK3 (10q21) and CACNA1C (12p13.3) were discovered previously in the same, combined schizophrenia and bipolar disorder sample." (PMID 23637625, 2013). "Notably, ITIH3, ITIH4, and NT5C2 were selected for depression, while PSMA4 and ITSN1 were identified for schizophrenia." (PMID 38637810, 2024).
COVID-19 (11 papers, 2021 to 2025). A disease caused by infection with severe acute respiratory syndrome coronavirus 2. "The alpha-trypsin inhibitor ITIH3 has been described in sepsis as well as to be related to mortality in severe COVID-19 and the activity of the serum paraoxonase PON1 has been shown to be predictive for 30-day mortality." (PMID 40898225, 2025). "From these proteins CRTAC1, IGLV3-1, HRG, HSPB1, LCP1, ITIH3, and APOA2 have all been identified as correlating with COVID-19 in other research, but to our knowledge, the rest are novel." (PMID 37308820, 2023). "Among those 5 features with significant time association, ITIH3 and LGALS9 levels appear elevated near symptom onset in severe COVID-19 but decline precipitously thereafter, unlike more stable trajectories in mild and moderate patients." (PMID 35839768, 2022).
depression (9 papers, 2016 to 2024). "Recent research in Japan found a close correlation between ITIH3 polymorphism and prenatal depression symptoms in a case–control study." (PMID 38637810, 2024). "Furthermore, the rs2535629 variant of ITIH3 is associated with the efficacy response to antipsychotic drugs, potentially impacting the treatment of mental health disorders, including depression." (PMID 38637810, 2024). "The decreased expressions of mRNAs in CUMS-induced depression mice include Slc6a11, Hap1, Gad1, Gad2, Gng4, Slc32a1, Doc2g, Slc32a1, Magel2, Prkcd, Ngfr, Dusp1, Th, Itih3, Cacna2d2, Arc, Mbp, Peg10, Fos, and so on." (PMID 27427907, 2016). "Three replicated loci were previously reported (ITIH3, FHIT, BAG5), but the other seven (ZNF804A, MIR3143, PSORS1C2, STK19, SPATA31D1, RTN1, TCF4) were novel for depression." (PMID 30626913, 2020).
gastric cancer (9 papers, 2015 to 2025). A primary or metastatic malignant neoplasm involving the stomach. "Studies have shown that ITIH3 is associated with the occurrence of colorectal cancer, gastric cancer, and endometrial cancer and can be used as a biomarker for the screening of these malignant tumors." (PMID 38410113, 2024). "Additionally, some of our identified biomarkers may contain several biological processes, such as ITIH3, which has also been previously associated with gastric cancer, hepatic steatosis, and psychiatric disorders." (PMID 40375290, 2025). "In two proteomic studies, ITIH3/ITIH4, as one of the serum differential proteins, was detected from the patients of hepatocellular cancer or gastric cancer, indicating a potential relation of ITIH3/ITIH4 to digestive system cancers." (PMID 31481982, 2019). "ITIH3 has also demonstrated antitumoral and antimetastatic properties, making it a potential biomarker for various types of cancer such as pancreatic cancer, prostate cancer, stomach cancer, and lung adenocarcinoma." (PMID 38375199, 2024). "ITIH3 belongs to the inter-α trypsin inhibitor (ITI) family of serine protease inhibitors, which are involved in the stabilization of extracellular matrix by covalently binding to hyaluronic acid, and has also been described to be overexpressed in plasma from gastric cancer patients." (PMID 37628784, 2023). "Moreover, other proteins revealed in both reports included upregulated A2GL (LRG1), ITIH3, ORM2 and SHGB, which collectively indicated very high conformity of serum proteome signature of gastric cancer that based on samples of unrelated Polish and India’s populations." (PMID 26376850, 2015).
bipolar disorder (5 papers, 2013 to 2023). A disorder of the brain that causes unusual shifts in mood, energy, activity levels and the ability to carry out day-to-day tasks. "Nevertheless, the whole-genome sequencing identified a number of rare and putative damaging variants in ANK3, ODZ2, ODZ4 and ITIH3 genes, located within or surrounding significant genome-wide association hits for bipolar disorder." (PMID 24625924, 2014). "For the ITIH3 locus, the same SNP was found as for the bivariate GWAS with bipolar disorder." (PMID 30626913, 2020).
breast carcinoma (5 papers, 2019 to 2025). "While RAB22A has been confirmed to be associated with breast cancer metastasis, few studies have investigated ITIH3 and CDV3." (PMID 40500539, 2025). "Referring to ITIH3, higher levels of ITIH3 in the plasma were reported in lung, pancreatic, and breast cancer, whereas opposite findings have been detected in colorectal cancer." (PMID 38480611, 2024).
colorectal cancer (5 papers, 2019 to 2024). A primary or metastatic malignant neoplasm that affects the colon or rectum. "As such, circulating ITIH3/4 levels are associated with carcinogenesis in colorectal cancer, and high ITIH4 levels correlate with a better prognosis in hepatocellular carcinoma." (PMID 38888758, 2024). "Expression of ITIH3 or ITIH4 in colorectal cancer and adjacent normal colorectal tissues was analyzed via IHC staining." (PMID 31481982, 2019). "According to the IHC score assessment, ITIH3 expression was dramatically reduced in colorectal cancer, compared with that in normal tissues (p < 0.001)." (PMID 31481982, 2019). "Expressions of ITIH3 and ITIH4 proteins in colorectal cancer and adjacent normal tissues were additionally examined via immunohistochemical (IHC) analysis." (PMID 31481982, 2019). "Consistently, IHC score assessment showed a dramatic reduction in ITIH3 expression and, conversely, upregulation of ITIH4 in colorectal carcinoma specimens relative to adjacent normal colorectal tissues (p < 0.001 in both cases)." (PMID 31481982, 2019). "log(P/(1-P) = -7.8709 + 4.5956 × IGFBP2 + 0.2732 × ITIH3 + 0.0909 × LRG1 + 0.1015 × C9 -3.2205 × CNDP1 + 0.0239 × ORM1 + 0.0811 × SERPINA1, where P is a value between 0 and 1 that represents the probability of the event (colorectal cancer)." (PMID 38383428, 2024).
Sepsis (5 papers, 2020 to 2026). Sepsis is defined as life-threatening organ dysfunction caused by a dysregulated host response to infection. "The decrease in ITIH1, ITIH2 and ITIH4, as compared to the increase in ITIH3, suggest a complex alteration in the protein balance of the IαI-family in sepsis." (PMID 40885913, 2025). "The decreased plasma levels of ITIH1, ITIH2 and ITIH4, as compared to the increased levels of ITIH3, suggest a complex alteration in the protein balance of the IαI-family in the pathophysiology of sepsis." (PMID 40885913, 2025). "SAA1;SAA2, CRP, ITIH3, SERPINA1 are acute phase proteins that are also dysregulated in other inflammatory states including sepsis." (PMID 36812516, 2022). "Peptides and/or phosphopeptides of common plasma proteins such as ITIH3, SAA2, SAA1, and FN1 showed increased observation frequency by Chi square (χ2 > 9, p < 0.003) and/or precursor intensity in sepsis." (PMID 32636717, 2020). "In agreement with the literature, peptides from ITIH3, SAA2, SAA1, and FN1 showed variation in observation frequency between ICU-Sepsis versus ICU Control." (PMID 32636717, 2020). "The application of 2D electrophoresis of blood fluid together with mass spectral analysis detected increased levels of serum amyloid (SAA1), inter alpha trypsin inhibitor (ITIH3) and APOJ in sepsis." (PMID 32636717, 2020). "The FN1, ITIH3, SAA1 and other peptides observed were consistent with previous claims of utility for these proteins as sepsis biomarkers." (PMID 32636717, 2020).
lung carcinoma (4 papers, 2008 to 2023). "Conversely, a significant increase in ITIH3 expression was observed in the plasma of patients with lung cancer." (PMID 36681849, 2023). "Earlier, Paris and coworkers revealed the roles of ITIH1 and ITIH3 in reducing the metastasis of lung cancer in mice while increasing cell attachment in vitro." (PMID 31481982, 2019). "Finally, ITIH1 and ITIH3 have been shown to increase cell attachment and to reduce the number of lung cancer metastases in mice." (PMID 18226209, 2008).
ovarian carcinoma (4 papers, 2010 to 2024). A malignant neoplasm originating from the surface ovarian epithelium. "In tumor biopsies, ITIH3 mRNA is reduced in tumor versus normal tissue in breast, uterus, colon, ovary, lung, rectum, and prostate cancer, and low protein levels were significantly associated with poor prognosis and platinum resistance in ovarian cancer." (PMID 38480611, 2024).
gestational hypertension (3 papers, 2022 to 2024). "Elevated expression levels of ITIH3 in the bloodstream have been found in cases of gestational hypertension and preeclampsia, suggesting its role as a mediator of thrombo-inflammation in these conditions." (PMID 38375199, 2024). "However, we discovered two novel ITIH protein biomarkers of preeclampsia, which have not been reported previously; ITIH3 and ITIH4 were both increased in EOPE and LOPE whereas ITIH2 was the only one increased in LOPE." (PMID 36351970, 2022).
hepatocellular carcinoma (3 papers, 2015 to 2024). A malignant tumor that arises from hepatocytes. "Both ITIH1 and ITIH3 encode one heavy chain of inter-alpha-trypsin inhibitor (ITI), which is one plasma protease inhibitor, and is synthesized and secreted in a hepatoma HepG2 cell culture and COS7 cell culture." (PMID 25946105, 2015).
myocardial infarction (3 papers, 2019 to 2024). Gross necrosis of the myocardium, as a result of interruption of the blood supply to the area, as in coronary thrombosis. "ITIH3 was answerable for advancement of myocardial infarction, but this gene may be associated with development of CAD." (PMID 31881747, 2019).
Obesity (3 papers, 2020 to 2024). Accumulation of substantial excess body fat. "Moreover, the inverse association of ITIH3 with obesity was also reported in experimental mouse models, and in participants with sustained weight loss following caloric restriction diets or bariatric surgery." (PMID 37676424, 2023). "ITIH3 may act as a carrier of hyaluronic acid in plasma and has been linked with obesity and MI." (PMID 37676424, 2023). "Some researchers have suggested the potential of targeting ITIH3 as a therapeutic approach for obesity." (PMID 38375199, 2024). "Combined with relevant experimental evidence, the findings of this study provide support for ITIH3 as a novel potential target for treatment of obesity." (PMID 37676424, 2023). "Other potential obesity biomarkers were found among those proteins elevated in vesicles from lipid hypertrophied cells such as inter-alpha-trypsin inhibitor heavy chain H3 (ITIH3), Glut4, cathepsin B, osteopontin, CD36, or tissue factor." (PMID 32214011, 2020). "However, there is a scarcity of data regarding the role of ITIH3 in obesity and metabolic disorders." (PMID 38375199, 2024).
pancreatic cancer (3 papers, 2020 to 2024). "Consistently, ITIH3, which has significant involvement in extracellular matrix remodeling during tumor progression, along with APOA1, APOE, APOL1, and CA19-9, constitutes a biomarker panel for pancreatic cancer." (PMID 37628784, 2023).
adrenocortical carcinoma (2 papers, 2021 to 2024). "Indeed, our work has shown that high ITIH3 expression is associated with reduced survival also in adrenocortical carcinoma, colon adenocarcinoma, kidney renal clear cell carcinoma, kidney renal papillary cell carcinoma and mesothelioma." (PMID 38480611, 2024).
Anxiety (2 papers, 2023 to 2024). Intense feelings of nervousness, tension, or panic often arise in response to interpersonal stresses. "After phenotype scanning, FOXO3 (rs3813498) was linked to intelligence and height, while ITIH3 (rs2071044) was associated with anxiety/tension." (PMID 39221148, 2024). "A previous study found that deletion of the alpha 1 microglobulin/bikunin precursor, which is necessary for the functional complex of ITIH1 or ITIH3, increases anxiety behavior, suggesting the involvement of Itih3 in mood disorders." (PMID 36794261, 2023).
autism (2 papers, 2020 to 2024). Persistent deficits in social interaction and communication and interaction as well as a markedly restricted repertoire of activity and interest as well as repetitive patterns of behavior. "In summary, this study presented a series of convergent lines of evidence that support ITIH3 rs25352629 as a susceptibility variant for autism in the Chinese Han population." (PMID 32251353, 2020).
diabetes (2 papers, 2024). "The association between certain diagnostic genes, such as ITIH3 and NRCAM, and diabetes remains understudied." (PMID 39296548, 2024). "We observed MR evidence for associations between genetically regulated levels of 7 proteins and HF risk factors including: SPON1, CCL15, and ITIH3 with hypertension; SVEP1 and SPON1 with atrial fibrillation; FSTL3 and NRP1 with diabetes; and APOF, CCL15, ITIH3, and NRP1 with CHD." (PMID 38225249, 2024).
Insulin resistance (2 papers, 2023 to 2025). Increased resistance towards insulin, that is, diminished effectiveness of insulin in reducing blood glucose levels. "ITIH3 is linked to tissue remodelling, and insulin resistance." (PMID 40000393, 2025).
thyroid cancer (2 papers, 2024). "In addition, Itih3 has previously been identified as a predictor of GC in mice and patients, while F12 is a prognostic marker for thyroid cancer." (PMID 38542101, 2024). "For instance, the expression of ANKRD6 and ITIH3 was associated with reduced OS in colon carcinoma (COAD) and kidney renal papillary cell carcinoma (KIRP), and the expression of CCDC178 in bladder urothelial carcinoma (BLCA) and thyroid carcinoma (THCA)." (PMID 38480611, 2024).
atrial fibrillation (1 paper, 2024). A disorder characterized by an electrocardiographic finding of a supraventricular arrhythmia characterized by the replacement of consistent P waves by rapid oscillations or fibrillatory waves that vary in size, shape and timing and are accompanied by an irregular ventricular response. "For the observed associations for NPPB, ITIH3, and IGFBP7 with multiple outcomes and for the association of SVEP1 with atrial fibrillation, our findings were negative for colocalization, suggesting two different causal variants for protein level and outcome." (PMID 38225249, 2024).
brain cancer (1 paper, 2008). A primary or metastatic malignant neoplasm affecting the brain. "Furthermore, ITIH3 has been shown to be a downstream target of Sonic hedgehog (Shh), which itself is know to be involved in pathogenesis of some human cancers, e.g. skin and brain cancers." (PMID 18226209, 2008).
colitis (1 paper, 2017). Inflammation of the colon. "After induction of acute colitis with DSS, we found with EdgeR and CuffDiff2 analyses that the expression of 11 genes (Clps, Ddx60, Fgb, Fgg, Ifi44, Ifit2, Isg15, Itih3, Itih4, Oas3 and Usp18), which are involved in antimicrobial response, was increased in MMP-9−/− compared to WT mice." (PMID 28561062, 2017).
hemorrhagic stroke (1 paper, 2023). A stroke caused by a bleed on the brain. "Agt and Itih3 was significantly upregulated after hemorrhagic stroke and Gjb6 showed the same tendency." (PMID 36794261, 2023).